FAM184A (family with sequence similarity 184 member A)
Synonyms: C6orf60; FLJ13942
Tractability: PROTAC: ubiquitination databases record sites on it.
Gene: Protein-coding gene on chromosome 6 (118,959,763 to 119,149,387, reverse strand). Ensembl gene ENSG00000111879.
Subcellular location: Cytoplasm, P-body; Cytoplasm, cytoskeleton, microtubule organizing center, centrosome, centriolar satellite
Subcellular location (Human Protein Atlas): Basal body; Centriolar satellite; Cytosol; Vesicles
Gene Ontology:
Molecular function: protein binding
Cellular component: centriolar satellite; ciliary basal body; extracellular region; P-body
Genetic constraint (gnomAD): Loss-of-function variants: 79 observed, 121.37 expected, observed/expected ratio (o/e) 0.65, 90% interval 0.54 to 0.79. The upper end of that interval is the gene's LOEUF score, 0.79, which puts it in group 3 of 6, group 1 being the genes least tolerant of losing a copy. Missense variants: 1,097 observed, 1,190 expected, observed/expected ratio (o/e) 0.92, 90% interval 0.88 to 0.97. Synonymous variants: 392 observed, 413.72 expected, observed/expected ratio (o/e) 0.95, 90% interval 0.87 to 1.03.
Homologues: Orthologues: chimpanzee FAM184A (99% identical), macaque FAM184A (98% identical), dog FAM184A (94% identical), pig FAM184A (94% identical), mouse Fam184a (89% identical), guinea pig FAM184A (86% identical), rat Fam184a (86% identical), tropical clawed frog fam184a (69% identical), zebrafish fam184ab (58% identical), zebrafish fam184aa (49% identical). Paralogues in human: FAM184B (26% identical).
Diseases named in the same sentence as FAM184A in open-access papers:
FAM184A is named in the same sentence as 12 diseases in open-access papers, as found by Europe PMC text mining. Sharing a sentence is not in itself a finding about the gene and the disease. The quoted sentences say what the papers report.
endometrial cancer (2 papers, 2020). Primary or metastatic malignant neoplasm involving the endometrium (mucous membrane that lines the endometrial cavity). "The biological function of FAM184A is unknown, but it was found to be increased in endometrial cancer and was classified as a risky prognostic gene." (PMID 33680913, 2020).
Cognitive impairment (1 paper, 2021). Abnormal cognition is characterized by deficits in thinking, reasoning, or remembering. "SNCA and FAM184A are associated with dyskinesias at baseline encounter, and SNCA is also associated with cognitive impairment." (PMID 33935957, 2021).
nervous system cancer (1 paper, 2020). A primary or metastatic malignant neoplasm involving the nervous system. "Interestingly, FAM184A has been found in a list of 88 pan-NET genes which are up-regulated in Neuroendocrine tumors (NETs) versus non-NETs in three different cancer types; prostate, lung and nervous system cancer." (PMID 32256978, 2020).
cancer (2 papers, 2020 to 2026). A tumor composed of atypical neoplastic, often pleomorphic cells that invade other tissues. "Pan-cancer analysis revealed the expression levels of FAM184A in different tumors, and it showed that high expression of FAM184A in SARC, SKCM, and PAAD is associated with improved prognosis and reduced mortality rates." (PMID 42081554, 2026).
FAM184A also shares sentences with these, for which no sentence is quoted: breast carcinoma (1 paper); chronic kidney disease (1); Dyskinesia (1); injury (1); lung carcinoma (1); Neuroendocrine tumors (1); osteoporosis (1); viral infection (1).